CDK8 (cyclin dependent kinase 8)
Diseases named in the same sentence as CDK8 in open-access papers (continued):
Sharing a sentence is not in itself a finding about the gene and the disease.
cancer (continued). "CDK8/CDK19 inhibitors can also enhance anti-tumour immunity, with current evidence suggesting that they act primarily in a cancer cell-extrinsic manner." (PMID 40163908, 2025). "CDK7, CDK8, and CDK9 are desirable targets for therapy since they have shown oncogenic roles in a variety of cancer types, such as colorectal, ovarian, and breast malignancies." (PMID 40361480, 2025). "A number of small-molecule CDK8/CDK19 inhibitors have been developed and their anti-cancer effects demonstrated in preclinical studies of multiple tumour types." (PMID 40163908, 2025). "Significant attention has been paid to the role that transcriptional CDKs play in cancer, including CDK7, CDK8, CDK9, CDK12, and CDK13." (PMID 40361480, 2025). "We have also determined CDK8/CDK19 RNA ratios in the same cell lines using our RNA-Seq data for 293 cells and RNA-Seq data of Cancer Cell Line Encyclopedia (CCLE) for all the other cell lines." (PMID 37378433, 2023). "We identify an immediate early transcriptional response that is strongly dependent on HIF1A and the kinase activity of its cofactor CDK8, includes indirect repression of MYC targets, and is highly conserved across cancer types." (PMID 33654095, 2021). "Cyclin C and CDK8 form part of the CDK8 kinase module of the RNAPII mediator complex, and deregulation of either gene has functional consequences for cancer development." (PMID 34329458, 2021). "Many H3S10-kinases, including MSK1/2, PIM1, CDK8 and AURORA kinases, have been long considered targets in cancer therapy." (PMID 33054831, 2020). "The potential for treatment of cancers directed toward the CKM and Cdk8 kinase activity is currently being investigated." (PMID 30621145, 2019). "MiR-101 exercises its biological function in multiple cancer types by interating with CXCR7, CDK8, EZH2 level and CPEB1." (PMID 27911279, 2017). "CDK8 is essential for the WNT signaling pathway – which enables cells to communicate with one another – and has been extensively studied in various cancers." (PMID 27935476, 2016). "CDK8 is a unique pharmacologic target in impaired fracture healing with clinically relevant, orally-bioavailable, non-toxic drugs already in cancer clinical trials 61–64." (PMID 40470203, 2025). "Cancer Cell Line Encyclopedia (CCLE) data analysis showed that RNA expression of CDK8 (but not of CDK19 or CCNC) was significantly higher in TNBC cell lines than in cell lines from other subtypes of BrCa." (PMID 39541354, 2024). "There is a growing body of evidence suggesting that other cyclin-dependent kinases including CDK7, CDK8, CDK9, and CDK12 may also be important for modulating the sensitivity of cancer cells to the effects of ionizing radiation." (PMID 34932500, 2022).
cancer (continued). "Whereas CDK19 and CDK20 are not essential in any of the cancer cell lines tested, there is a minor proportion of cell lines in which CDK8 (~ 3%), CDK10 (~ 1%), CDK12 (~ 27%) and CDK13 (~ 3%) are essential." (PMID 36577800, 2022). "Finally, we propose an innovative strategy for potential combinatory treatment with CDK8/19 inhibitors that stabilize MED13, and significantly potentiate cancer cell killing by alkylating drug." (PMID 33444446, 2021). "Actually, several transcription-associated CDK inhibitors, including CDK7i (CT7001, SY-1365, SY-5609 and LY3405105), CDK8/19i (SEL120), and CDK9i (Alvocidib, TP-1287, BAY1251152 and AZD4573) have now progressed to Phase I/II clinical trials in various cancer types." (PMID 33686962, 2021). "AURKA and IDH3B are not present in any of the lists of cancer genes, whereas CDK8, MARCH7, YAP1, and YES1 are found among the more than 9000 candidate cancer genes identified by forward genetic screens in mice." (PMID 33427197, 2021). "As most of these CDK8-dependent pathways are altered in cancer, it is not surprising that CDK8 has been proposed to contribute to tumor development." (PMID 32596239, 2020). "As most of the described CDK8-dependent pathways are altered in cancer, it is not surprising that CDK8 has been proposed to contribute to tumor development." (PMID 31248103, 2019). "Pharmacological inhibition of CDK8 and CDK19 by the steroidal alkaloid Cortistatin A (CA), deregulates expression of tumor suppressors and lineage-controlling genes in AML and results in suppressed growth of cancer cells." (PMID 28422713, 2017). "Amplification and mutation of genes encoding CDK8, CycC, and other subunits of Mediator complex have been identified in a variety of human cancers, however, the function and regulation of CDK8-CycC in non-disease conditions remain poorly understood." (PMID 26222308, 2015). "Prior to this study, the role of circ-CDK8 in cancer cells had not been reported." (PMID 39170701, 2024). "Yet genetic confirmation of requirements for CDK8 in cancers in vivo has been lacking." (PMID 36545778, 2023). "Thus, despite their established roles as regulators of Mediator, and considerable interest in their therapeutic targeting in cancer, we do not yet fully understand the redundant and specific roles of CDK8 and CDK19." (PMID 36545778, 2023). "We further demonstrate the therapeutic potential of MED13-mediated response, by applying combinatory treatment with CDK8/19 inhibitor Senexin A. Importantly, the treatment with Senexin A stabilizes MED13, and in combination with alkylating agents significantly reduces viability of cancer cells." (PMID 33444446, 2021). "Collectively, these results suggest that SEL120-34A inhibits IFN-dependent gene expression, however the effects on these genes are modest and transient, indicating that CDK8 is not a major driver of STAT-dependent transcription in IFN-stimulated cancer cells in vitro." (PMID 28422713, 2017). "Since the individuals of the present study are healthy and present no type of cancer, it seems that CDK8–CCNC may act as components of the normal cell repair machinery, because CDK8 also phosphorylates several other proteins, many of which are related to DNA repair and transcription." (PMID 34444642, 2021). "CDK8, MET, PRKCZ, and PTK2 also exhibit negative scores against the majority of the cells, indicating inhibition of these hub genes could arrest cell proliferation required during cancer." (PMID 40500799, 2025). "The identification of cancer types with frequent amplification of CDK8 and correlation of expression with survival suggests a potential role of CDK8 in the pathogenesis of CRC or its treatment response, but it does not necessarily imply that such cancers will respond to CDK8 inhibitor therapy." (PMID 32596239, 2020).
tumor (94 papers, 2009 to 2026). "CDK8 is associated with up-regulating β-catenin activity, which aids in tumor development, invasion, and metastasis." (PMID 40361480, 2025). "Mutations in CDK8, a protein kinase, are also implicated as a primary factor associated with tumor formation." (PMID 38615023, 2024). "In patient #19, fifteen oncogenic mutations were CDX tumor-exclusive, affecting genes such as CDK8, COP1, and MAP2K2." (PMID 36980717, 2023). "Circ_0005576 has been demonstrated to be overexpressed in CRC and was associated with tumor malignant progression through the miR-874/CDK8 axis in CRC." (PMID 35378711, 2022). "Loss of CDK8 allows to overcome immune evasion programs that counteract NK-cell-mediated recognition of the primary tumor." (PMID 34689158, 2021). "To confirm that NK cells are the key players for tumor control of CDK8-deficient E0771 cells in Rag2−/− mice, we performed depletion experiments using an αNK1.1 antibody." (PMID 34689158, 2021). "In AML cell lines, inhibition of CDK8/CDK19 kinase activity upregulates SE-associated genes with tumor suppressor and lineage-controlling functions, thereby exerting anti-leukemic effects." (PMID 31628323, 2019). "The effects of the CDK8/19i and everolimus on stromal proteins implicated in tumor growth could contribute to in vivo suppression of tumor models (such as 4T1 and MDA-MB-231) that were not responsive in vitro." (PMID 39541354, 2024). "Hence, prevention of in vivo adaptation to everolimus by the CDK8/19i is associated with effects on the expression of multiple tumor and stromal genes that regulate tumor growth and drug response." (PMID 39541354, 2024). "Our results provide preliminary evidence that CDK8/19 inhibition may regulate inflammatory profiles of tumor-associated macrophages." (PMID 37376593, 2023). "To address the relevance of CDK8 in NK-cell-mediated recognition in an in vivo setting, we orthotopically injected CDK8-deficient and wild-type tumor cells into recombination activating gene 2 knockout (Rag2−/−) mice that rely on NK cells for tumor surveillance but lack T and B cells." (PMID 34689158, 2021). "The enhanced in vivo efficacy may be attributable to the effects of CDK8/19i on the tumor microenvironment (TME) caused by suppressing tumor-promoting paracrine activities of stromal fibroblasts and stimulating the antitumor activity of NK cells, as seen in other models." (PMID 40149277, 2025). "Combined CDC7 and CDK8 inhibition significantly reduced proliferation and colony-forming ability, led to ≥4 N DNA content, and reduced tumor volume and mass in vivo." (PMID 42031714, 2026). "In the current study, MED12 WT tissues treated with GnRH agonists exhibited both stronger tumor shrinkage and a lower level of CDK8 activity compared to the untreated group." (PMID 41493967, 2026). "Critically, both tumor types harbored the identical missense mutation c.131G > A (p.Gly44Asp) in exon 2, a known hotspot that disrupts MED12-Cyclin C binding and impairs CDK8/19 kinase activity within the Mediator transcriptional complex." (PMID 41156195, 2025). "Taken together, these data confirm the enhanced efficacy of CDK8/19is, particularly when combined with platinum-based chemotherapy, evidenced by the inhibition of tumor growth, decreased cellular proliferation and vascularity, and improved overall survival." (PMID 40149277, 2025). "A recent study showed that CDK8/CDK19 inhibition reversed the castration-resistant phenotype of CRPC tumours in vivo by modifying the oncogenic transcriptional responses to castration." (PMID 40163908, 2025). "In natural killer (NK) cells, CDK8/CDK19 inhibition augments production of key cytolytic molecules to increase tumour kill and enhance response to anti-PD-1 immunotherapy." (PMID 40163908, 2025).
tumor (continued). "Inhibiting the activity of mediator kinase (CDK8/19) in acute myeloid leukemia can upregulate the SE activity related to a tumor suppressor and activate the expression of the tumor suppressor gene, thus achieving anti-leukemia activity." (PMID 40672386, 2025). "Similar to the in vitro molecular biomarkerdata, the tumor STAT1SER727 phosphorylation data indicatea partial redundancy between CDK8 and CDK19 loss, with CDK8 inhibitionplaying a greater role than CDK19 in the molecular response to CCT251921treatment in vivo." (PMID 40601435, 2025). "Our findings revealed that circ-CDK8 is a critical tumor-promoting factor, and it regulates protein expression by modulating RNA-protein interactions or through RNA splicing." (PMID 39170701, 2024). "Due to the significance of CDK8 as a tumor-promoting factor, CDK8 inhibitors have been developed for the treatment of malignancies." (PMID 38606172, 2024). "CDK8/19i are unique among anticancer drugs, since they rarely inhibit the proliferation of tumor cells but more often suppress the adaptation of such cells to environmental challenges, such as metastatic growth or therapy." (PMID 39541354, 2024). "Previous studies confirmed that CDK8 is an important oncogenic factor, making it a potential tumor biomarker and a promising target for tumor therapy." (PMID 38606172, 2024). "Combining everolimus with a CDK8/19 inhibitor counteracted many of these changes and induced combination-specific effects on the expression of multiple genes that affect tumor growth." (PMID 39541354, 2024). "Remarkably, many of the stromal genes were affected not only by systemic treatment with a CDK8/19i but also by Mediator kinase mutagenesis in tumor cells alone, suggesting that CDK8/19 activity in the tumor cells molds the tumor microenvironment." (PMID 38546787, 2024). "We found that MKI reverses the castration-resistant phenotype of CRPC tumors in vivo, by altering the transcriptional effects of castration on both tumor and stromal genes, whereas prolonged administration of a CDK8/19i induces tumor regression and cures." (PMID 38546787, 2024). "In the context of BrCa, CDK8/19i were found to inhibit tumor growth, prevent the development of estrogen independence and potentiate antiestrogens in ER-positive BrCa." (PMID 39541354, 2024). "Knockdown of CDK8 inhibited tumor growth and prolonged the survival of intracranial tumor-bearing mice relative to shNull, reinforcing CDK8 as a crucial factor controlling the growth of MYC-amplified MB." (PMID 39574899, 2024). "Based on the findings of a previous study on circRNA (Gao, Zhao, Li, Dou, Wang, Liu, Ren and Zhi, 2019), we first evaluated the expression of circ-CDK8 in 43 OSCC tumor tissues and matched normal samples." (PMID 39170701, 2024). "Both systemic treatment with a CDK8/19i and Mediator kinase mutagenesis in tumor cells affect stromal gene expression." (PMID 38546787, 2024). "CDK8/19i also suppress tumor growth and prevent and reverse resistance to HER2-targeting drugs in HER2-positive BrCa." (PMID 39541354, 2024). "To understand the role of Mediator kinases in CRPC, we analyzed their effects on transcription and tumor growth using both mutagenesis of CDK8 and CDK19 and pharmacological inhibition of Mediator kinases in 22Rv1, a “classical” androgen-independent CRPC model." (PMID 38546787, 2024). "Prolonged CDK8/19 inhibitor treatment combined with castration not only suppressed the growth of CRPC xenografts but also induced tumor regression and cures." (PMID 38546787, 2024). "Systemic CDK8/19i treatment suppresses androgen-independent in vivo growth and produces tumor regression and cures in 22Rv1 xenografts." (PMID 38546787, 2024). "The expression level of circ-CDK8 is tightly associated with clinical characteristics, such as TNM stage, histological grade, tumor size and postoperative survival rate of OSCC patients." (PMID 39170701, 2024).
tumor (continued). "CDK8/19i treatment also suppressed tumor growth in 3 AR-positive PDX models derived from PCa patients, at least 2 of whom failed ADT and chemotherapy." (PMID 38546787, 2024). "We further investigated the clinicopathologic characteristics of OSCC patients and found that the expression of circ-CDK8 positively correlated with tumor size, lymph node metastasis and histological grade." (PMID 39170701, 2024). "The overexpression of miRNA-101 or enriched exosome uptake by macrophages suppresses IL1A and IL6 expression by targeting CDK8, whereas injecting miR-101 into xenografted tumors reduced growth and macrophage tumor infiltration in vivo." (PMID 38002256, 2023). "CDK8 is part of the Mediator complex that regulates transcription and can function as either a tumor suppressor or an oncogene in different contexts." (PMID 33686962, 2021). "Under the influence of CDK8/19 inhibitors,tumor cells went from the stem phenotype to a differentiated state." (PMID 33959383, 2021). "As our data suggest that tumor-intrinsic CDK8 controls NK-cell immune evasion in a kinase-independent manner, CDK8/CDK19 kinase inhibitors would not suffice to reach a clinical benefit." (PMID 34689158, 2021). "We here show that tumor-intrinsic CDK8 regulates invasiveness and metastatic capacity of TNBC cells and shields the tumor cells from NK-cell-mediated recognition and killing in a kinase-independent manner." (PMID 34689158, 2021). "A direct link between CDK8 and β-catenin regulation in tumor cell proliferation and death has also been described, where inactivation of CDK8 by siRNA transfection in HCT116 cells significantly reduced the RNA and protein levels of β-catenin." (PMID 35002699, 2021). "Surgical removal of the primary tumor was consistently performed at a tumor size of 75 mm2, and the persistent knockdown of CDK8 was confirmed." (PMID 34689158, 2021). "This led us to conclude that CDK8 in TNBC cells blocks NK-cell-mediated tumor recognition in a kinase-independent manner." (PMID 34689158, 2021). "This led us to conclude that tumor-intrinsic CDK8 promotes regrowth of tumors and distant metastasis formation in the orthotopic TNBC mouse model." (PMID 34689158, 2021). "Knockdown of CDK8 in TNBC cells impairs tumor regrowth upon surgical removal and prevents metastasis." (PMID 34689158, 2021). "In summary, these data define a role of tumor-cell-intrinsic CDK8 as an immune checkpoint controlling NK-cell-mediated tumor recognition." (PMID 34689158, 2021). "Primary tumor growth was significantly delayed in mice transplanted with CDK8-knockdown cells, indicating an enhanced NK-cell-mediated tumor surveillance of the primary tumor." (PMID 34689158, 2021). "Elemene combined with chemotherapy decreased CDK8 gene expression levels in tumor tissues of a Lewis lung cancer mouse model." (PMID 34641334, 2021). "TCGA is an invaluable resource to comprehensively analyze the transcriptome profile of CDK8 across a large spectrum of the most common tumor entities from thousands of patients." (PMID 32596239, 2020). "Specific deletion of CDK8 in NK cells results in an enhancement of their anti-tumor responses, an activity that heavily relies on the action of different cytokines on natural killer (NK) cells." (PMID 33357429, 2020). "Further investigation revealed that the downregulation of VGLL4 upregulated the expression of apoptosis-related Bcl-2 and the cell-cycle regulators Cyclin D1, Cyclin E1, and CDK8, and the upregulation of these molecules was conducive to tumor proliferation." (PMID 31748508, 2019). "CDK8 deletion in the NK cell compartment using Cdk8fl/fl Ncr1Cre transgenic mice partially recapitulates the enhanced NK cell-mediated cytotoxicity and tumor surveillance by upregulating the cytolytic effector protein Perforin." (PMID 31248103, 2019). "On the other hand, the phosphorylation of linker domain promotes Smad ubiquitination and degradation, which has been reported to be regulated by Cdk8 in tumor cell lines." (PMID 31552016, 2019).